IL10 (interleukin 10)
Diseases named in the same sentence as IL10 in open-access papers (continued):
Sharing a sentence is not in itself a finding about the gene and the disease.
autoimmune disease (continued). "CD24 on transitional B cells represents a central developmental stage in B-cell maturation, producing high levels of IL-10, which is considered to be related to chronic inflammatory and autoimmune diseases, including multiple sclerosis, rheumatoid arthritis, and systemic lupus erythematosus." (PMID 40612664, 2025). "Insufficient production or dysregulation of IL-10 disrupts the balance between pro-inflammatory and anti-inflammatory responses, contributing to the progression of autoimmune diseases such as rheumatoid arthritis, multiple sclerosis, and systemic lupus erythematosus." (PMID 40084163, 2025). "Its functions include the maintenance of gut-associated lymphoid tissue (GALT), interactions with macrophages, and the regulation of T regulatory (Treg) lymphocytes—which are essential for preventing autoimmune diseases—partly by promoting their development and the release of interleukin-10 (IL-10)." (PMID 40868207, 2025). "Additionally, autoimmune diseases lead to chronic inflammation, resulting in the secretion of various inflammatory factors such as IL-6, IL-10 and TGF-β, which play significant roles in tumor progression." (PMID 39744497, 2025). "Regulatory B-cells (CD24hiCD38hi) play a vital role in controlling autoimmune diseases such as RA, mediated via secreting anti-inflammatory cytokines including IL10 to restrain inflammation and promote the differentiation of immunoregulatory T cells and inhibit the differentiation of Th17 cells." (PMID 40908179, 2025). "The lower percentages of mBregs can influence B cell mediated suppression, contributing to diminished induction of IL-10+ T cells in children with T1D or C. Thereby, this could possibly be a contributing factor to the development of another autoimmune disease." (PMID 38134245, 2024). "As previous studies have indicated that IL-10 secreting plasma cells or plasmablasts may play a regulatory role in autoimmune diseases, a decrease in IL-10 production by NOD.Ifih1R/R CD138+ cells may support enhanced inflammation during diabetes." (PMID 38487540, 2024). "Therefore, these immunoregulatory functions of IL-10 suggest its potential therapeutic role in preventing inflammatory and autoimmune diseases." (PMID 39104791, 2024). "The evaluated cytokines can be classified into three broad groups: the proinflammatory Th-1 cytokines: IL-2, IFN-γ, and TNF-α; the counterbalancing Th-2 cytokines: IL-4, IL-5, IL-10, and IL-13; and the Th-17 cytokine IL-17A, which is actively involved in several autoimmune diseases including MS." (PMID 38932415, 2024). "Interleukin 10 (IL-10) plays a central role in preventing autoimmune diseases." (PMID 38607023, 2024). "To our knowledge, this is the first time that DUSP6 KO mice are studied in a model of autoimmune disease, and we show that these mice are significantly protected and have reduced levels of pro-inflammatory cytokines, and increased levels of IL10 and IL10-producing cells." (PMID 38974475, 2024). "Activation of A2AR inhibits NF-κB signaling pathway and inflammatory cytokine (IL-1, IL-6, TNF, IFN) production, and increases the anti-inflammatory cytokine IL-10 release, which leads to autoimmune diseases such as rheumatoid arthritis, systemic lupus erythematosus, or type 1 diabetes." (PMID 38837964, 2024). "However, defective IL-10 signaling can lead to the development of autoimmune diseases, in which the immune system mistakenly attacks the body’s own tissues." (PMID 39541341, 2024). "Furthermore, mesoporous silica NPs were chosen for the encapsulation of IL-10 mainly because of a few significant features that make them particularly suitable for use in controlling inflammation within an autoimmune disease setting." (PMID 38893150, 2024). "IL-10 plays a critical role in slowing the progression of autoimmune diseases." (PMID 39697331, 2024).
autoimmune disease (continued). "IBD is classified as an autoimmune disease, and regulation of the proinflammatory activity of cytokines by anti-inflammatory and immunosuppressive cytokines such as IL -4 and IL-10 may be helpful in controlling the severity of such diseases." (PMID 37735396, 2023). "However, B lymphocytes also play an important role in the pathogenesis of autoimmune diseases through IL-10 and PD-L1 molecules." (PMID 38813034, 2023). "However, few studies have examined the role of iNOS and IL-10 secreted by MDSCs in autoimmune diseases." (PMID 36969174, 2023). "Indeed, IL-10-producing Breg cells (B10) have been shown to play an important role in the inhibition of autoimmune diseases and inflammations." (PMID 37759658, 2023). "Blocking or potentiating IL-10 signalization by artificially evolved non-antibody binders such as H33 could be an important component of the treatment of inflammatory, malignant and autoimmune diseases in which IL-10 plays a role." (PMID 37555209, 2023). "Similarly, SP1 and JUN have been shown to function together to induce TNF expression in response to viral infection and SPI1 has been shown to promote IL10 expression —a cytokine often seen to be dysregulated in autoimmune diseases as in PR3+ AAV." (PMID 36768148, 2023). "However, the reason why chronic microbial infections can inhibit type 2 immunity cell-mediated autoimmune diseases involves IL-10–dependent counter-regulation." (PMID 37978564, 2023). "The sparing effect of Stevia extract on the IL-10 levels may point to its role in modulating immune responses and inflammation, fostering tissue repair and wound healing, and reducing autoimmune diseases and chronic inflammatory disorders." (PMID 37836640, 2023). "These immune components are responsible for production of inhibitory cytokines such as interleukin 10 (IL-10) and transforming growth factor-β (TGF-β), which may lower the risk of developing clinically significant autoimmune disease." (PMID 37182047, 2023). "The activated anti-idiotypic Treg cells secrete IL-10, and IL-10 suppresses Th2 cell responses to allergens and autoimmune T cell responses to self-antigens and thus can induce a long-term clinical remission of allergic and autoimmune diseases." (PMID 38094290, 2023). "The increase of IL-10 induced by CUR and RES in vitro could prospectively reflect a potential effect of these polyphenols in vivo, regulating inflammatory processes in autoimmune diseases and tumor associated-inflammation." (PMID 38203402, 2023). "IL-10-secreting Bregs are now regarded as negative regulators of the immune system, inflammation and autoimmunity, based on studies in humans and mouse models of autoimmune diseases such as rheumatoid arthritis, SLE and MS." (PMID 37375483, 2023). "IL-1β is an effective activator of dendritic cell subsets and a regulator of T-cell differentiation and function; in contrast, IL-10 is the most crucial cytokine to inhibit the proinflammatory response and limit the overimmune response of various autoimmune diseases." (PMID 35302166, 2022). "IL10 gene encodes for a pleiotropic anti-inflammatory cytokine and several polymorphisms on this gene have been identified with possible consequences on the response to TNF-i treatment in other autoimmune diseases, such as RA and inflammatory bowel disease." (PMID 35887591, 2022). "IL-10 has controversial effects on different autoimmune diseases (SLE vs. MS)." (PMID 35031055, 2022). "Furthermore, we observed the level of IL-10 production in the culture medium; this is a major immunosuppressive cytokine that plays a crucial role in preventing inflammatory and autoimmune diseases." (PMID 35681372, 2022). "One might speculate that the elevated Tfh/Treg ratio together with the presence of increased levels of IL10 are signs of the unrestrained immune reactions in severe COVID-19 disease courses which resemble ongoing autoimmune diseases." (PMID 36293090, 2022).
autoimmune disease (continued). "IL-10 is a well-known cytokine possessing a strong immunosuppressive effect; however, its use as an immunosuppressant for treating autoimmune diseases in the clinical settings has been limited by its short terminal half-life (approximately 2.7–4.5 h) and rapid clearance in vivo." (PMID 35255957, 2022). "IL-10 overexpression may rapidly induce even the amount of Treg cells, thus contributing to a milder course of autoimmune diseases, including type 1 diabetes." (PMID 36091019, 2022). "Tregs work as key effective suppressors in autoimmune diseases, not only suppressing the proliferation of Th0 cells in vitro and in vivo but also exerting their function by producing the immunomodulatory cytokines, such as IL-10 and TGF-β." (PMID 35126527, 2022). "Iwata and colleagues further explored IL-10+ B cell frequencies in 91 patients with several autoimmune diseases (SLE, RA, primary Sjögren’s syndrome, autoimmune vesiculobullous skin disease, or MS), and found that numbers were not significantly lower in these patients compared to healthy controls." (PMID 36179248, 2022). "IL-10 is involved in the pathogenesis of autoimmune diseases, including RA, diabetes, and SLE." (PMID 36422613, 2022). "The role of SphK1 activity in mediating the TNF-α-induced decrease in IL-10 as well as the decrease in TNF-α itself has important translational implications in other inflammatory disorders, particularly those associated with autoimmune diseases such as inflammatory bowel disease." (PMID 35409108, 2022). "IL-10 is an inflammatory cytokine that has an inhibitory effect on autoimmune diseases." (PMID 36443718, 2022). "Since dysregulation of IL-10 is associated with an increased risk of developing many autoimmune diseases, the ability of this system to correct the functionality of IL-27 and subsequent IL-10 expression levels is a promising therapeutic approach to treat several autoimmune diseases." (PMID 36009412, 2022). "IL-10 plays an important role in down-regulating the inflammatory cascade by enhancing anti-inflammatory cytokines and slowing down the production of pro-inflammatory cytokines and preventing autoimmune diseases." (PMID 34204516, 2021). "Our study revealed that, although Tregs lacking miR-21 produce significant more IL-17 and IL-10 when under pathogenic Th17-priming condition, miR-21-deficiency in Tregs is largely dispensable for the development of autoimmune disease." (PMID 34858422, 2021). "The IL-10 derived from MCs has beneficial effects in the maintenance of tissue homeostasis and has detrimental effects in several immune-related diseases, including autoimmune diseases, inflammation, rejection, and infections." (PMID 34067047, 2021). "IL-10 is an important immune regulator of many autoimmune diseases and inflammatory conditions." (PMID 35010153, 2021). "IL-10 is a significant anti-inflammatory cytokine in autoimmune disease." (PMID 34150746, 2021). "Th 1 cytokines, such as TNF-α and IFN-γ, are known to lead the progression of autoimmune diseases such as type 1 diabetes and multiple sclerosis (MS), while IL-4, IL-10, and IL-13 refer to Th 2 cytokines and inhibit the pro-inflammatory response and reduce damage." (PMID 34445510, 2021). "IL-10 plays a role in the prevention of autoimmune disease by downregulating secretion of pro-inflammatory cytokines from effector T helper cells and reducing expression of co-stimulatory molecules on macrophages, and correct temporal release of IL-10 is critical for resolution of inflammation." (PMID 36474817, 2021). "Also, in autoimmune diseases and recovery after inflammatory injury, the co-expression of IFN-γ and IL-10 has been associated with favorable responses." (PMID 34868005, 2021). "IL-10 is an anti-inflammatory cytokine and can inhibit inflammation in autoimmune diseases." (PMID 33932995, 2021).
autoimmune disease (continued). "However, aberrant expression of IL-10 can not only enhance inflammatory response to microbial challenge but also lead to development of inflammatory bowel disease and a number of autoimmune diseases." (PMID 33841067, 2021). "Because IL-10 and IL-35 play critical roles in regulating immunity during autoimmune diseases, we investigated whether capacity of CD4-IR4KO T cells to produce these anti-inflammatory cytokines might also be altered during EAU." (PMID 33803441, 2021). "In chronic inflammatory and autoimmune diseases as well as in cancerous conditions, IL-10 is involved in the regulation of the delicate balance between protective immunologic effector responses and the limitation of exaggerated inflammation as well as the maintenance of immune tolerance." (PMID 33572870, 2021). "IL-10 limits the immune response and prevents tissue damage in infection and autoimmune disease." (PMID 32695123, 2020). "In addition, the IL10-dependent suppressive role for the Breg cells has been proven in different models of autoimmune diseases, including SLE, rheumatoid arthritis, and multiple sclerosis." (PMID 32775471, 2020). "Therefore, at this time point, a definitive conclusion regarding the role of MDSCs/IL-10 in autoimmune disorders cannot be made." (PMID 32931721, 2020). "Bregs cells have been recently described as an essential immune system component that exhibits downregulatory function by suppressing the adaptive and innate arms of the immune system, inflammation reactions, and autoimmune diseases, mainly through the secretion of IL10." (PMID 32775471, 2020). "IL-10 is an important anti-inflammatory cytokine that plays a crucial role in preventing various inflammatory pathologies especially in tumor and autoimmune diseases, through reducing the function of antigen-presenting cells, and inhibiting T cell proliferation and Th1/Th17 cell differentiation." (PMID 33101289, 2020). "To mimic an imbalance between pro- and anti-inflammatory cytokines as reported for the pathogenesis of autoimmune diseases, we added neutralizing anti-IL-10 antibody to the cell culture supernatants (medium + anti-IL-10, mock SN+ anti-IL-10, BV SN + anti-IL-10, EC SN + anti-IL-10)." (PMID 33542719, 2020). "T helper 1 (Th1) anti-inflammatory cytokines IL-4 and IL-10 are involved in the maintenance of homeostasis and, in particular, in controlling pro- and anti-inflammatory cytokines involved in infectious, allergic and autoimmune diseases." (PMID 32879392, 2020). "In addition, MDSCs promote the expansion of Breg cells (IL-10-producing B cells) via an iNOS-dependent pathway and ameliorate autoimmune disorders." (PMID 33317573, 2020). "Although it is well-established that IL-10 producing Tregs suppress inflammation and organ-specific autoimmune diseases, recent studies have identified regulatory B cells (Bregs) that secrete IL-10 and/or IL-35 as critical regulators of immunity during autoimmune diseases." (PMID 33004854, 2020). "Studies have demonstrated that through inflammatory stimuli, T-bet-expressing MZ B cells secrete IL-10, suggesting that T-bet might contribute to the remission of autoimmune diseases by activating the regulatory potential of MZ B cells." (PMID 32973780, 2020). "IL-10 plays a crucial role in inflammatory and autoimmune diseases of the intestine, chronic infections, tumor development, neuroinflammation, -degeneration as well as multiple organ dysfunction syndrome (MODS) and MOF after polytrauma, where IL-10 levels from 21.0 to 340.7 pg/mL were shown." (PMID 32492963, 2020). "Interestingly, successful treatment (i.e., complete remission) with Rituximab of the autoimmune disease pemphigus vulgaris is characterized by a higher number of IL-10 producing Breg post-treatment compared to cases with incomplete remission." (PMID 33036432, 2020).
autoimmune disease (continued). "Recent research indicated that the inhibition of B cell metabolism mediated by two synergistic cytokines, TGF-β and IL-10, contributes to the induction of immune tolerance and could be a new therapeutic strategy for autoimmune diseases such as SLE." (PMID 31240224, 2019). "TGF-β and IL-10 producing Treg cells are crucial immune response regulators in autoimmune diseases." (PMID 31380412, 2019). "Therefore, using IL-10 as a therapeutic agent seems to be ambivalent due to its pleiotropic effects in different autoimmune diseases." (PMID 31036055, 2019). "IL-10 plays important roles in many autoimmune diseases such as RA." (PMID 31661005, 2019). "Hypothetically, NKT expanded from PBMC of patients exposed for a few hours to α-GalCer could induce anti-inflammatory cytokines (IL10), as previously reported, downregulating polyclonal activation of T and B cells and related symptoms in autoimmune diseases." (PMID 29389901, 2018). "Interestingly, the balance between IFN-γ and IL-10 has been reported to be critical in the pathogenesis of autoimmune diseases." (PMID 29672707, 2018). "Further, we demonstrated that the therapeutic effect of GM-CSF was primarily mediated through the mobilization of CD11c+CD8α− DCs that could stimulate the expansion of Tregs in vivo and suppress autoimmune disease through increased IL-10 production." (PMID 30297856, 2018). "IL10 is an anti-inflammatory cytokine and its primary function is to limit inflammatory responses, which has been well studied in the pathogenesis of several autoimmune diseases including EAE45." (PMID 29445144, 2018). "IL-10 is an important anti-inflammatory cytokine that inhibits proinflammatory mediator production and lymphocyte proliferation, thus playing a protective role in autoimmune diseases." (PMID 30648118, 2018). "Despite growing evidence highlighting the relevance of increasing IL-10-producing B cells (B10+cells) in autoimmune diseases, their functions in patients are still unknown." (PMID 29774031, 2018). "MDSCs could reciprocally regulate Th17/Treg cells and suppress CIA via IL-10, suggesting that MDSCs might be a promising therapeutic strategy for T cell mediated autoimmune diseases including RA." (PMID 29491381, 2018). "Therapeutically, fostering of HIF-1α expression may provide a tool to increase IL-10-producing B cells and limit autoimmune diseases such as EAE and arthritis." (PMID 29343683, 2018). "However, TGF-β and IL-10 also have pleiotropic effects and induce humoral immune responses depending on conditions, and thus their therapeutic application to autoimmune diseases remains limited." (PMID 29963056, 2018). "We suggested that the CD11c+CD8α− DC subset may play a role in the amelioration of autoimmune diseases through Treg expansion and increased IL-10 production." (PMID 30297856, 2018). "Therefore, overexpressed MALAT1 induces tDCs and immune tolerance in transplantation and autoimmune disease by the miR155/DC-SIGH/IL10 axis." (PMID 30150986, 2018). "Therefore, overexpressed MALAT1 induces tDCs and immune tolerance in heart transplantation and autoimmune disease by the miRNA-155/DC-SIGH/IL10 axis." (PMID 30150986, 2018). "The participation of regulatory B cells in the immune homeostasis exerted by vitamin D seems to be confirmed in murine models of autoimmune diseases in which a functioning pathway mediated by IL-10 is required to guarantee the effect of 1,25(OH)2D3 on the disease." (PMID 30205552, 2018). "Discovery that IL-12p35 can also induce IL-10 or IL-35-producing Treg/Breg cells offers the promise of Treg and Breg immunotherapy and would facilitate investigations on the role of i35-Bregs and iTR35 cells in autoimmune diseases and cancer." (PMID 29051763, 2017). "Interestingly, IL-10 can have dual effects on autoimmune diseases: acting as a B cell stimulator and also suppressor of T cell activations." (PMID 28456914, 2017).